TRUB2 (TruB pseudouridine synthase family member 2)
Description:
Minor enzyme contributing to the isomerization of uridine to pseudouridine (pseudouridylation) of specific mitochondrial mRNAs (mt-mRNAs) such as COXI and COXIII mt-mRNAs. As a component of a functional protein-RNA module, consisting of RCC1L, NGRN, RPUSD3, RPUSD4, TRUB2, FASTKD2 and 16S mitochondrial ribosomal RNA (16S mt-rRNA), controls 16S mt-rRNA abundance and is required for intra-mitochondrial translation. Also catalyzes pseudouridylation of some tRNAs, including synthesis of pseudouridine(55) from uracil-55, in the psi GC loop of a subset of tRNAs.
Synonyms: CLONE24922
Tractability: PROTAC: ubiquitination databases record sites on it.
Gene: Protein-coding gene on chromosome 9 (128,305,159 to 128,322,741, reverse strand). Ensembl gene ENSG00000167112.
Subcellular location: Mitochondrion matrix
Pathways (Reactome):
Metabolism of RNA: Mitochondrial mRNA modification; rRNA modification in the mitochondrion
Gene Ontology:
Molecular function: pseudouridine synthase activity; RNA binding; tRNA pseudouridine(55) synthase activity
Biological process: mitochondrial tRNA pseudouridine synthesis; mRNA pseudouridine synthesis; positive regulation of mitochondrial translation; mRNA modification; pseudouridine synthesis; RNA modification; RNA processing
Cellular component: mitochondrial matrix; mitochondrion; ribonucleoprotein granule
Genetic constraint (gnomAD): Loss-of-function variants: 33 observed, 35.69 expected, observed/expected ratio (o/e) 0.92, 90% interval 0.7 to 1.24. The upper end of that interval is the gene's LOEUF score, 1.24, which puts it in group 5 of 6, group 1 being the genes least tolerant of losing a copy. Missense variants: 451 observed, 454.83 expected, observed/expected ratio (o/e) 0.99, 90% interval 0.92 to 1.07. Synonymous variants: 201 observed, 188.44 expected, observed/expected ratio (o/e) 1.07, 90% interval 0.95 to 1.2.
Homologues: Orthologues: chimpanzee TRUB2 (98% identical), macaque TRUB2 (92% identical), pig TRUB2 (87% identical), mouse Trub2 (81% identical), dog TRUB2 (81% identical), guinea pig TRUB2 (80% identical), rat Trub2 (76% identical), tropical clawed frog trub2 (56% identical), zebrafish trub2 (48% identical), Drosophila melanogaster CG7849 (28% identical), Caenorhabditis elegans Y43B11AR.3 (22% identical).
Diseases named in the same sentence as TRUB2 in open-access papers:
TRUB2 is named in the same sentence as 11 diseases in open-access papers, as found by Europe PMC text mining. Sharing a sentence is not in itself a finding about the gene and the disease. The quoted sentences say what the papers report.
breast carcinoma (2 papers, 2022 to 2024). "Elevated expressions of FARS2 and TRUB2 have been noted in breast cancer tissues, and C2orf15 expression significantly correlates with breast cancer prognosis, although their link to ER status needs further investigation." (PMID 39720180, 2024).
lung carcinoma (2 papers, 2023 to 2024). "Among epitranscriptomic genes, we found QTRT, a queuine tRNA ribosyltransferase known to be induced in lung cancer, and TRUB2, a pseudouridine synthase essential for mitochondrial protein synthesis." (PMID 37620598, 2023). "In lung cancer (LUAD, LUSC), DKC1, PUS1, PUS3, PUS7, TRUB1, and TRUB2 expression was mostly negatively correlated with immune cell infiltration." (PMID 39162904, 2024).
age (1 paper, 2023). A temporal measurement of the time period elapsed since an identifiable point in the life cycle of an organism. "FAM129B is a new regulator of Wnt/β-catenin-dependent phenotypes in melanoma cells, and TRUB2 is an age-associated cancer marker." (PMID 36609218, 2023).
glioma (1 paper, 2024). A benign or malignant brain and spinal cord tumor that arises from glial cells (astrocytes, oligodendrocytes, ependymal cells). "Results revealed that TRMT2B, TRMT11, METTL8, TRMT6, and TRUB2 were upregulated in glioma, while METTL6 was downregulated." (PMID 38824202, 2024).
Sepsis (1 paper, 2023). Sepsis is defined as life-threatening organ dysfunction caused by a dysregulated host response to infection. "For instance, genes mediating RNA Ψ modification (TRUB1, TRUB2, PUS1, RPUSD3, RPUSD4, PUS7, RPUSD2) were mainly suppressed in sepsis." (PMID 37701433, 2023).
thyroid cancer (1 paper, 2023). "We found five TAD blocks with CoMut genes/events specific to ATC with certain mutation frequency in The Cancer Genome Atlas Thyroid Cancer (TCGA-THCA) cohort, including CoMut pairs MAST/NSUN4, AM129B/TRUB2, COL5A1/PPP1R26, PPP1R26/GPSM1/CCDC183, and PRAC2/DLX4." (PMID 36609218, 2023).
cancer (6 papers, 2016 to 2026). A tumor composed of atypical neoplastic, often pleomorphic cells that invade other tissues. "RPUSD1 exhibited markedly elevated expression across pan‐cancer tissues, followed by TRUB2, TRUB1, and PUS3." (PMID 41496500, 2026). "However, limited studies have examined the effect of TRMT2B, TRMT11, and TRUB2 in cancers." (PMID 38824202, 2024). "A few genes, such as TRUB2 and HNRNPA2B1, are consistently expressed across most cancer types, primarily due to their involvement in fundamental biological processes or their roles in large biomolecular complexes." (PMID 40867324, 2025). "Only three genes including Dolichol Kinase (DOLK), TruB Pseudouridine Synthase Family Member 2 (TRUB2), and Ubiquitin Related Modifier 1 (URM1) were identical between normal and cancer tissues." (PMID 30388870, 2018).
tumor (2 papers, 2024). "Strikingly, patients exhibiting elevated levels of PUS1, PUS3, PUSL1, RPUSD1-4, and TRUB2 demonstrated a significantly shorter disease-free survival, as evidenced by combined analysis with tumor disease-free survival data." (PMID 39247811, 2024). "Both PUS1 and TRUB2 were aberrantly expressed in 79% of the tumor types." (PMID 39162904, 2024). "The most affected tumor type was PRAD, in which the expression of five synthases, DKC1, PUS3, RPUSD4, PUS7, and TRUB2, had mostly negative effects on DSS." (PMID 39162904, 2024).
TRUB2 also shares sentences with these, for which no sentence is quoted: melanoma (1 paper); prostate adenocarcinoma (1); prostate carcinoma (1).